CXCL5 (C-X-C motif chemokine ligand 5)
Diseases named in the same sentence as CXCL5 in open-access papers (continued):
Sharing a sentence is not in itself a finding about the gene and the disease.
tumor (continued). "In our tumor model, however, BMMC injection did not alter the expressions of SDF-1 and CXCL5 in tumor microenvironment (data not shown)." (PMID 20111717, 2010). "The CXCR2-ADRA1A function module generated from our data included several immune-related genes, such as CXCL5, CXCL13, RGS12, and CXCR1, indicating that the DNA methylation function module might involve in the immune response regulation in the tumor microenvironment of sMPLC." (PMID 36611170, 2023). "Promoting tumor cell recognition by DCs can up-regulate the expression of chemokines, such as chemokine (C-X-C motif) ligand 1 protein (CXCL1) and chemokine (C-X-C motif) ligand 5 protein (CXCL5), and increase the infiltration and proliferation of immune cells at the site of tumor." (PMID 37040283, 2023). "Serum levels of CXCL5 were significantly higher in intermediate or advanced disease stages (BCLC B/C) when compared to early stage disease (BCLC 0/A), indicating a role for this chemokine as potential biomarkers for tumor progression and spread in cirrhotic patients." (PMID 36982370, 2023). "Besides, critical chemokine ligand family members (including CXCL1, CXCL2, CXCL5, CXCL8, and CXCL11), which involved in tumor growth regulation and metastasis and mediated the enrichment of CD8+ T cells into the TME, were upregulated in the high AI score subtype." (PMID 36245985, 2022). "Also, CXCL5 promotes tumor angiogenesis, and new blood vessels act as tumor metastasis channels; CXCL5/CXCR2 can release matrix metalloproteinase-9 (MMP-9), destroys endothelial cells and matrix barrier, and promotes tumor metastasis." (PMID 33869023, 2021). "Importantly, CXCL1 concentration in tumor lysates was found to be significantly higher than in plasma from corresponding mice, whereas the level of CXCL5 did not significantly differ in tumor and plasma samples." (PMID 33578808, 2021). "Furthermore, inflammatory cytokines secreted in the tumor microenvironment enhance COX-2 expression and local release of prostaglandin E2 (PGE2), which boosts tumor and stromal cell expression of proangiogenic VEGF, CXCL8, and CXCL5." (PMID 34943797, 2021). "We further used TTCM to activate neutrophils in the presence or absence of CXCL5 neutralizing antibody to see whether CXCL5 in gastric microenvironment boost tumor development by regulating neutrophils." (PMID 32632106, 2020). "Therefore, we investigated whether CXCL5, CXCL9, and CXCL10 expression was correlated with immune infiltration levels in GC using the Tumor Immune Estimation Resource (TIMER) database." (PMID 33323542, 2020). "Furthermore, as cytokines can assist tumor progression, targeting IL-4, IL-13, IL-10, TGF-β, and CXCL5 or enhancing IFN-γ and some chemokines (e.g., CCL2, CCL3, CXCL9, CXCL10) may inhibit tumor invasion and metastasis." (PMID 32346605, 2020). "Furthermore, CXCL5 was identified as the major driver of HCC cell invasion and tumor formation." (PMID 30014484, 2019). "The expression of both CXCL5 and CXCR2 was higher in the NPC primary tissues than in the non-tumour tissues at the protein level as quantified by IHC, and the expression of CXCL5 was primarily localized to the tumour cells rather than the mesenchymal portion of the cancerous tissue." (PMID 29665837, 2018). "Moreover, the expression of CXCL5 was primarily localized to the tumor cells rather than the mesenchymal portion of the cancerous tissue." (PMID 28356111, 2017). "The greatest difference in average concentration between tumor and plasma was found for CXCL5 (186-fold gradient) as the chemokine was largely not detectable in patient plasma, while in tumor lysates, its concentration was highest of all analyzed CXCR2 ligands." (PMID 28923105, 2017). "Recently, the CXCR2 receptor for the granulocyte- and platelet-derived ligand CXCL5/7 was shown to be important for recruitment of neutrophils to early metastatic niches, and CXCR2 inhibitors reduce the recruitment of granulocytes in primary tumor sites as well." (PMID 26966341, 2016).
tumor (continued). "However the ability of CCL2, CXCL1, CXCL5 and VEGF to significantly reduce IL-12p70 production by DCs is important, as this may potentially result in a reduced anti-tumour Th1 response in vivo." (PMID 22125641, 2011). "However, at the protein level, there was up-regulation of CXCL5/ENA78, CCL20/MIP3-α, IGFBP3, OPN and TIMP1 in tumours and their PN, indicating that these could be early events in the gastric tumorigenesis." (PMID 21092330, 2010). "In tumor neighbor tissues of CRLM we detected no substantial CXCL5 reactivity." (PMID 18578857, 2008). "Considering the results of other studies on CXCL5 molecular signal transduction, ERK1/2-signaling-induced cell migration is mainly generated in tumor cells, which may be due to the activation of ERK1/2 by multiple growth factors and their receptors in tumor cells." (PMID 37373052, 2023). "Remarkably, our results presented significant alterations between the CXCL5 concentration in stage IV/III + IV of CRC and healthy controls, and significant differences between all TNM stages, which may indicate its contribution to the development of tumor progression and distant metastasis." (PMID 37848726, 2023). "Unlike S100A8/A9, the abundance of CXCL1, CXCL2, and CXCL5 chemokines in scaffolds neither increased following the infiltration of cancer-induced neutrophils in MNs after tumor inoculation nor decreased after systemic depletion of neutrophils in tumor-bearing mice." (PMID 37553342, 2023). "The major population of TAMs is composed of CD163+ M2 polarized macrophages, and anti-tumor agents (e.g., IFN-α, IFN-β, or IFN-γ) could activate TAMs, which, once activated, could increase serum soluble (s)CD163 and release various autoimmune related chemokines such as CXCL5." (PMID 29050354, 2017). "We treated ER+ tumor cells (MCF7) with fulvestrant in the presence or absence of the top five secreted cytokines (GROα/CXCL1, IL-8, CXCL5, hepatocyte growth factor (HGF) and CCL19)." (PMID 37423299, 2023). "Next, we analyzed the expression of CXCL5, CXCL8, IL18RAP, and TREM2 in paired tumor and adjacent normal tissues." (PMID 33955820, 2021). "Engulfment of cancer cells, but not normal cells, resulted in the production of C-X-C motif chemokine ligand 5 (CXCL5) and other pro-inflammatory cytokines, which led to immunosuppression and rebounding tumor growth." (PMID 32059476, 2020). "Immunohistochemistry staining showed abundant and uniform expression of CXCL5, CXCL9, and CXCL10 proteins in nontumor adjacent gastric tissues (N), but expression of these proteins was significantly downregulated in all tumor samples (C)." (PMID 33323542, 2020). "A difference was found between male mice with and without primary tumor differed in IL-10 and IL-16 levels, which were higher in those with tumor, and in CXCL5, CXCL11, CXCL13, CXCL16, and CCL24 levels, which were higher in those without tumor." (PMID 32545680, 2020). "In our study, CXCL5 was primarily secreted by tumour tissues rather than by the mesenchymal cells, and the NPC cell lines were capable of expressing CXCL5." (PMID 29665837, 2018). "The results of the cell growth and foci formation assays revealed that the overexpression of CXCL5 and/or CXCR2 did not influence NPC cell growth, tumour formation or cell proliferation." (PMID 29665837, 2018). "We also observed that CXCL5 was primarily expressed in tumor lesions, rather than the mesenchyme of cancer tissue, and CRC cell lines were capable of secreting CXCL5." (PMID 28356111, 2017). "We found that expression of CXCL1, but not CXCL5, decreased significantly in patients with low TGFBR2 expression, but when we analyzed subtypes of tumor we discovered significant differences only in HER2+, PR + and ER + patients." (PMID 25280532, 2014). "As in the tumor tissue, TGFβ upregulated IL-6 and, VEGF, and downregulated MCP1, CXCL1, and CXCL5 in cells with and without DNIIR expression." (PMID 25280532, 2014).
tumor (continued). "Interestingly, although the status of macrophage and CXCL5 expression was not changed by TGF-β1 stimulation, the conditioned media of TGF-β1-treated macrophages enhanced the 3D tumor growth." (PMID 40050422, 2025). "Like CXCL5, CXCL2 could be an ancestry-related chemokine; however, CCL23 is a novel chemokine that appeared to be independent of ancestry, and its role in tumor suppression warrants further investigation." (PMID 37698493, 2023). "While patterns of CXCR2 in immune cells were not consistent with the patterns of immune cells induced by CXCL5, CXCR3 was highly expressed in T cells in the tumour microenvironment of PAAD tissue, which was in agreement with the induced patterns change of immune cells induced by CXCL9/10." (PMID 31913856, 2020).
cancer (264 papers, 2010 to 2026). A tumor composed of atypical neoplastic, often pleomorphic cells that invade other tissues. "For example, a meta-analysis of multiple cancer types showed that elevated CXCL5 levels was associated with lower overall survival, progression-free survival and recurrence-free survival." (PMID 41392310, 2025). "IL-6, which has previously been linked to muscle wasting in cancer patients, was also upregulated, but at a lower level than CXCL5." (PMID 41392310, 2025). "As our findings showed that Vox strongly reduced neutrophils in tumors, we analyzed the expression of Cxcl1, Cxcl2 and Cxcl5 (genes encoding neutrophil-recruiting chemokines) in FACS-sorted cancer cells, total immune cells, neutrophils and macrophages." (PMID 40139833, 2025). "More specifically, Cxcl5-deficient cancer cells exhibit reduced expression of enzymes and metabolites pertaining to glycolysis, serine/glycine biosynthesis, and one-carbon metabolism." (PMID 40050422, 2025). "Collectively, the results indicate that loss of Cxcl5 impedes the global reprogramming of metabolic pathways critical for cancer growth in a 3D environment." (PMID 40050422, 2025). "PAI1triggered the formation of cancer-associated macrophages (CAMs), which in turn produced interleukin-8 (IL-8) and C-X-C motif chemokine ligand 5 (CXCL5), promoting the metastasis of OC cells through a feedback mechanism." (PMID 39583124, 2024). "C-X-C motif chemokine ligand 5 (CXCL5) can bind to CXCR2 on cancer-associated fibroblasts (CAFs), thereby promoting the expression of PD-L1 and enhancing the therapeutic effectiveness of anti-PDL1 in CRC19." (PMID 38049474, 2023). "Next, we further investigated the mechanism underlying the increased secretion of CXCL5 on cancer cells following AB680." (PMID 37867243, 2023). "In PC, the hyperactivated Hippo–YAP signaling causes the upregulation of CXCL5 in cancer cells, which promotes the MDSCs recruitment via the CXCL5–CXCR2 axis." (PMID 35860573, 2022). "Other top differentiated genes that resulted from the presence of platelets included cancer-associated inflammatory cytokines CXCL5 and CCL5 which are associated with invasiveness, metastasis and platelet guided formation of a metastatic niche." (PMID 34189439, 2021). "CXCL5 acts as a protumor molecule in different cancer types and it is associated with neutrophil trafficking, cancer angiogenesis, progression and resistance to therapies." (PMID 32854690, 2020). "While some studies associate higher CXCL5 expression with a worse cancer prognosis, several reports indicate that a lower CXCL5 expression can also promote metastatic spread." (PMID 31226820, 2019). "In serum, sTWEAK levels positively correlated with sCCL7 and sCXCL5, and it is known that high expression of CXCL5 is closely related to cancer progression, which is in line with the association we observed in our cohort between PSA levels and sCXCL5 in urine." (PMID 31500625, 2019). "Through systematic analysis, our results demonstrated that high expression level of CXCL5 was significantly associated with poor OS in cancer patients." (PMID 29743818, 2018). "Hazards ratios (HR) with corresponding 95% confidence intervals (CI) were pooled to estimate the association between CXCL5 expression levels with survival of cancer patients." (PMID 29743818, 2018). "The pooled HR for OS was 1.70 (95% CI 1.36–2.12, p < 0.001), which suggested that elevated expression level of CXCL5 was significantly associated with poor OS in cancer patients." (PMID 29743818, 2018). "In addition, this gene was found to co-express with MMP1 and CXCL5 in a subset of cancer-associated fibroblasts associated with poor clinical outcome." (PMID 41489684, 2026). "Numerous previous studies have linked CXCL5 expression to reduced survival in cancer patients." (PMID 41392310, 2025). "Moreover, the levels of other checkpoint molecules, such as TIM3, TIGIT, and CTLA4, were significantly associated with CXCL5 in multiple forms of cancer." (PMID 39670859, 2025).
cancer (continued). "Thus far, our data indicate that PTN-stimulated NF-κB activation causes cytokine expression especially CXCL5 in cancer cells, which leads to neutrophil recruitment." (PMID 36828390, 2023). "CXCL5 in cancer-associated fibroblasts promotes PD-L1 expression to enhance immune inhibition." (PMID 36290882, 2022). "The sources of CXCL5 may be associated with cancer cell autocrine and paracrine loop in the tumor microenvironment (TME), transmitting signals by binding to the IL-8B receptor (CXCR2)." (PMID 35646113, 2022). "Cancer cells induce CXCL5 and cause NET formation through the DDR1/PKCθ/NF-κB signaling pathway." (PMID 34237033, 2021). "Moreover, there was a trend that CD68+CXCL5+ macrophages in the stroma around the edges of the cancer nests to be associated with MUC1-ST expression." (PMID 33149188, 2020). "Furthermore, both CD163 and CXCL5 are highly associated with inflammatory infiltrates, which are frequently detected in the lumen of malignant prostate glands.A relationship between the TWEAK/Fn14 axis and CD163 was also found in urine." (PMID 31500625, 2019). "The results of subgroup analysis illustrated that the association between increased expression level of CXCL5 with poor OS of cancer patients was still significant in all factors above except for the subgroup of studies with fewer than 100 patients (HR 1.60, 95% CI 0.81–3.17, p = 0.175)." (PMID 29743818, 2018). "Therefore, we suspect the spheroid growth defect of Cxcl5-deficient cancer cells may result from a combined deficit in energy, biomass, and antioxidant production." (PMID 40050422, 2025). "Moreover, paracrine CXCL5 secreted by cancer-associated stromal cells (mesenchymal stem cells and macrophages) could also promote cancer cell invasion and dissemination." (PMID 33458757, 2021). "Moreover, CXCL5 expression has been found to be associated with the degree of malignancy, metastatic potential, and degree of inflammatory infiltration in numerous types of cancer." (PMID 33458757, 2021). "The results presented in this study reveal a new aspect of CAF-derived CXCL5 secretion in the progression of cancer cachexia." (PMID 41392310, 2025). "While CXCL5 secreted by immune cells or fibroblasts reportedly plays an important role in modulating the composition and activities of immune cells in the TME, little is known about the role cancer-derived CXCL5 plays in cancer progression." (PMID 40050422, 2025). "To study the role of cancer-derived CXCL5 in the growth of M1-CM-treated spheroids, we deleted Cxcl5 in Panc02 cells using CRISPR/Cas9 and performed a 3D spheroid-in-Matrigel culture of wild-type (WT) or Cxcl5−/− Panc02 cells with or without M0- or M1-CM." (PMID 40050422, 2025). "In conjunction with our observed increase in macrophage SREBP1, there were simultaneous increases in Arg1, Cxcl5, and Il6, all of which can promote cancer progression in different cancers." (PMID 41462606, 2025). "We postulate that the role of CAF-secreted CXCL5 in cancer cachexia is due to activation of the CXCL5 receptor CXCR2 in skeletal muscle." (PMID 41392310, 2025). "The patients’ cancer tissues analyzed in this study all showed elevated CXCL5 immunostaining in the stromal region." (PMID 41392310, 2025). "CXCL5 neutralization ameliorated muscle wasting induced by CXCL5 and IL-6 co-treatment, and also prevented atrophy in cancer-activated CAF CM-treated human myotubes." (PMID 41392310, 2025). "CXCL5 have been described as a ‘coachman’ that drives cancer progression via immunosuppression, angiogenesis and metastasis." (PMID 41392310, 2025). "In vivo RNA seq of the TA muscle was used to identify the mechanisms by which CXCL5 neutralization prevents cancer cachexia." (PMID 41392310, 2025). "Using this culture system, we discovered an unanticipated role for cancer-derived Cxcl5 in the metabolic reprogramming of cancer cells as they adapt to the 3D TME." (PMID 40050422, 2025).